ENO1 (enolase 1)
Diseases named in the same sentence as ENO1 in open-access papers (continued):
Sharing a sentence is not in itself a finding about the gene and the disease.
brain cancer (1 paper, 2024). A primary or metastatic malignant neoplasm affecting the brain. "Notably, genes linked to brain cancer progression and tumor immunity (ENO1, MUC1, COL5A1, and IL11) were significantly downregulated (>2-fold) in KO brain tissue but were upregulated in FABP7 OV astrocytes." (PMID 39596296, 2024). "We also found that the expression of the onco-immune factors (ENO1, MUC1, COL5A1, IL11) that we identified was significantly correlated with FABP7 expression in patient brain cancers, particularly LGG, suggesting the pathological relevance of the results of our transcriptomic analyses." (PMID 39596296, 2024).
Cerebral ischemia (1 paper, 2021). Restriction of arterial blood supply to the brain associated with insufficient oxygenation to support the metabolic requirements of the tissue. "Furthermore, proteins as HSC70, DRP2, enolase 1, UCHL1, ADK1, and particularly NDKA and even more Rho-GDI, exhibit higher association levels to 4E-BP2 in cerebral cortex and could be considered as biomarkers of resilience to cerebral ischemia." (PMID 34638676, 2021).
cervical tumor (1 paper, 2017). "According to the available data in the Human Protein Atlas, most of tested cervical tumor samples were positive for protein expression of EGR3, NR4A2, SOX9, PA2G4, ENO1, and TEAD4." (PMID 28670312, 2017).
cholangitis (1 paper, 2014). An acute or chronic inflammatory process affecting the biliary tract. "Plasma levels of ENO1 and RNH1 autoantibodies in cholangitis were significantly higher compared to healthy individuals (P<0.01)." (PMID 25058392, 2014). "We demonstrated that plasma ENO1 autoantibody levels are also significantly increased in CCA and cholangitis compared to healthy control." (PMID 25058392, 2014). "Diagnostic performance of autoantibodies against HSP70, RNH1 and ENO1 in pairwise comparisons between CCA, cholangitis, or healthy controls." (PMID 25058392, 2014). "In addition, circulating ENO1 and RNH1 autoantibodies levels were also significantly higher in cholangitis and CCA compared to healthy controls (P<0.05)." (PMID 25058392, 2014). "Anti-HSP70, ENO1 and RNH1 autoantibodies levels could be distinguished between healthy controls and cholangitis (P<0.01, AUC = 0.8170, 0.8043 and 0.7790, respectively)." (PMID 25058392, 2014). "Further, plasma ENO1 and RNH1 autoantibodies were higher in CCA compared to cholangitis but failed to reach statistical significance." (PMID 25058392, 2014).
chordoma (1 paper, 2013). Chordomas are rare malignant tumors arising from embryonic remnants of the notochord in axial skeleton. "Our mRNA microarray results showed that ENO1, PKM2, and Gp96 were upregulated in chordoma tissue relative to notochord tissue." (PMID 23826111, 2013).
chronic gastritis (1 paper, 2025). Inflammation of the stomach that is chronic in nature. "It has also been presented the mRNA expression level of Recombinant Enolase 1 (ENO1) in chronic gastritis and precancerous lesions in the H. pylori infection group were obviously higher than in the non-infection group." (PMID 40051725, 2025).
colitis (1 paper, 2024). Inflammation of the colon. "We observed a reduced relevant abundance for hexokinase (HK1), glucose-6-phosphateisomerase (GPI), phosphofructokinase (PFKL), fructose 1,6-biphosphate aldolase enzymes (ALDOA, ALDOB), triosephosphate isomerase (TPI), phosphoglycerate kinase 1 (PGK1), and alpha enolase (ENO1) in colitis." (PMID 38668322, 2024).
colon adenocarcinoma (1 paper, 2022). "It was found that ATP5A1 and ENO1 were positively correlated with the infiltration of CD4+ T lymphocytes in colon adenocarcinoma and a negative correlation between GADPH and PDIA3 with the infiltration of NK cells and CD4+ T lymphocytes in rectal adenocarcinoma, respectively." (PMID 35445138, 2022).
colorectal tumor (1 paper, 2024). "Proteins that regulate glycolysis (PGK1, PGAM1, ENO1, PKM, TKT), ammonia detoxification (GLUD1), and other metabolic pathways (LDHA, GAPDH, MDH2) were reported to be differentially expressed in mouse xenograft colorectal tumor models with different radio- responsiveness." (PMID 38410100, 2024).
dengue virus infection (1 paper, 2020). "For example, GAPDH regulates hepatitis A virus, hepatitis C virus and human parainfluenza virus infection and ENO1 regulates Sendai virus and dengue virus infection." (PMID 32917235, 2020).
disseminated candidiasis (1 paper, 2020). Systemic candidiasis occurs when Candida yeast enters the bloodstream and may spread (becoming disseminated candidiasis) to other organs, including the central nervous system, kidneys, liver, bones, muscles, joints, spleen, or eyes. "Both passive and active vaccinations with C. albicans Eno1 display protective effect against disseminated candidiasis." (PMID 33115324, 2020).
ductal carcinoma (1 paper, 2024). "In the lobular and mixed lobular and ductal carcinomas, ENO1 was underexpressed for almost all signalling, immune, and epigenetic pathways." (PMID 39483155, 2024). "Interestingly, ENO1 shows clustering with all the major immune pathways in DCIS and high-grade tumours but only with interferon signalling and lymphoid compartment in ductal carcinoma." (PMID 39483155, 2024).
dyslipidemia (1 paper, 2008). "Dyslipidemia could be confounding the association of the ENO1 SNP with MI since this SNP trended toward association with dyslipidemia (P = 0.1)." (PMID 18682748, 2008).
end-stage renal disease (1 paper, 2024). "The most common non-HLA antibodies were anti-ENO1 (28.4%), anti-FIBR1 (23.0%) and anti-PRKCZ (23.0%), indicating their possible involvement in the immune responses of patients with end-stage renal disease on the kidney transplant waiting list." (PMID 39596170, 2024).
endometrial atypical hyperplasia (1 paper, 2015). "In order to further assess the role of ENO1 in EC, we measured the expression levels and subcellular localization of ENO1 protein in 20 normal NE tissues, 22 endometrial atypical hyperplasia (EAH) and 100 archived paraffin-embedded EC samples using immunohistochemical staining." (PMID 25951350, 2015).
epilepsy (1 paper, 2025). A brain disorder characterized by episodes of abnormally increased neuronal discharge resulting in transient episodes of sensory or motor neurological dysfunction, or psychic dysfunction. "In addition, the mTOR pathway genes RPS6, TPI1, ENO1, and PGK1 are enriched in PY2-like cortical neurons of brain samples from patients with epilepsy compared with people in a nonepilepsy control group." (PMID 40026248, 2025).
erectile dysfunction (1 paper, 2025). Persistent or recurrent inability to achieve or to maintain an erection during sexual activity. "Currently, direct evidence implicating ENO1 in the pathogenesis of erectile dysfunction is lacking." (PMID 40859388, 2025).
erythroleukemia (1 paper, 2005). Acute erythroid leukemia characterised by the presence of at least 50% erythroid precursors and at least 20% myeloblasts in the bone marrow. "However, the transfection of ENO1-mRNA into K562 cells, a human erythroleukemia cell line, shows only minor differences with control mRNA." (PMID 16359544, 2005).
Ewing sarcoma (1 paper, 2025). A small round cell tumor that lacks morphologic, immunohistochemical, and electron microscopic evidence of neuroectodermal differentiation. "In an animal model of Ewing sarcoma, ENO-1+ CD63+ EVs were elevated along with tumor growth and reduced after tumor resection." (PMID 40679665, 2025). "Importantly, increased ENO-1+ CD81+ EVs in the patient serum before treatments can distinguish patients with Ewing sarcoma from healthy individuals with an area under the curve of 0.92 and reflected the tumor burden in Ewing sarcoma patients during multidisciplinary treatments." (PMID 40679665, 2025).
familial Alzheimer disease (1 paper, 2025). A degenerative disease of the brain that causes gradual loss of memory, judgment, and the ability to function socially. "Furthermore, integration with data from familial Alzheimer's disease indicated ALDOA, ENO1, PKM and PGAM1 are all upregulated in the early to middle stages of disease onset." (PMID 40491829, 2025).
gastric tumors (1 paper, 2012). "Although we observed two up-regulated spots of ENO1 in the proteomic analysis, the mean expression of ENO1 was reduced in gastric tumors by western blot." (PMID 22860099, 2012).
glaucoma (1 paper, 2019). Increased pressure in the eyeball due to obstruction of the outflow of aqueous humor. "Furthermore, some previous identified glaucoma autoantigens including heat shock protein 60 dDA (HSPD1), heat shock protein 70 kDa (HSPA1B), vimentin (VIM), α-enolase (ENO1) and superoxide dismutase 1 (SOD1) could be detected." (PMID 30899261, 2019).
H. pylori (1 paper, 2022). "This study reveals that ENO1 expression is associated with H. pylori (cagA+) infection, cagA transfection, co-culture duration, MOI, gastric normal/cancer cell lines and cellular differentiation." (PMID 36295613, 2022).
hepatitis B virus infection (1 paper, 2022). A viral infection caused by the hepatitis B virus. "In hepatitis B virus infection, knock-down ENO1 expression can reduce viral replication by up-regulating type I interferon." (PMID 35130884, 2022).
Hypertension (1 paper, 2025). The presence of chronic increased pressure in the systemic arterial system. "As a crucial therapeutic target, Eno1 has been reported to be closely associated with cancer, hypertension, and infectious diseases." (PMID 39853121, 2025).
immune deficiency (1 paper, 2017). "We know that having a good boost of early IL-1 production is good for priming the innate immune system, thus the reduced production of IL-1 in Chlamydia pulsed ENO1 knockdown DCs constitutes an immune deficiency in the clearance of Chlamydia." (PMID 28525970, 2017).
infertile (1 paper, 2021). "Antibodies against ENO1, ALDOA, GAPDH, and ODF1 were also detected in human semen from infertile men." (PMID 34576131, 2021).
intestinal cancer (1 paper, 2022). "The expression of ENO1 in dozens of intestinal cancer cell lines was evaluated in Depmap Portal, online database of Cancer Cell Line Encyclopedia (CCLE)." (PMID 36620599, 2022).
invasive breast carcinoma (1 paper, 2017). A carcinoma that infiltrates the breast parenchyma. "In particular, quantification of the expression of EPO, ETS1, PGK1, TPI, LDHA and ENO1 in a primary tumor sample provides information on the risk of recurrence for patients with early-stage invasive breast cancer." (PMID 28430808, 2017).
invasive carcinoma (1 paper, 2024). A carcinoma that is not confined to the epithelium, and has spread to the surrounding stroma. "Analysis on disease progression and histological types showed ENO1 overexpression in ductal in situ and invasive carcinoma, in high-grade tumours followed by advanced or metastasis and was linked to worse survival." (PMID 39483155, 2024).
kidney stone (1 paper, 2016). "From these, the increased level of enolase-1 was confirmed by Western blot analysis and its significant role in kidney stone formation was addressed." (PMID 27045290, 2016).
knee osteoarthritis (1 paper, 2023). "This study shows synovial fluid FBG downregulation and ENO1 upregulation could be useful biomarkers in diagnosing knee osteoarthritis." (PMID 37373906, 2023).
lentivirus infection (1 paper, 2025). Virus diseases caused by the Lentivirus genus. "These constructs were expressed in ENO1‐KO PANC‐1 and MIA PaCa‐2 cells by lentivirus infection to assay their stem cell‐like properties." (PMID 40298941, 2025).
liver diseases (1 paper, 2017). "Our previous study indicated that the presence of autoantibody against ENO1 may be a predictive marker for better prognosis of liver diseases." (PMID 28456790, 2017).
Liver Inflammation (1 paper, 2025). "Importantly, inhibiting ENO1-mediated glycolysis with ENOblock effectively attenuated KC pyroptosis, highlighting the pivotal role of ENO1 in HS-induced liver inflammation and injury." (PMID 40943261, 2025).
mastitis (1 paper, 2022). Inflammation of breast tissue during lactation or postpartum due to an obstructed duct or infection. "When mastitis developed (T1/C1), GPI, TPI1, GAPDH, PGK1, PGAM1, ENO1, and PKM in the glycolysis/gluconeogenesis pathway were upregulated, which promoted pyruvate synthesis with large amounts of ATP production." (PMID 36335251, 2022).
myelogenous leukemia (1 paper, 2015). "Our findings suggest that elevated level of enolase 1 and aldolase C may contribute directly or indirectly to the chemoresistance demonstrated by doxorubicin-resistant myelogenous leukemia cells and the cells need more energy through glycolysis to survive when exposed to chemical stress." (PMID 25628518, 2015).
myopia (1 paper, 2022). "In order to explore the role of ENO1 in the pathogenesis of myopia, the expressions of ENO1 in the retina of groups I, II, and III were detected by immunoblotting." (PMID 36439692, 2022). "Recent studies have shown that hypoxia is the key mechanism of myopia, and ENO1 is closely related to hypoxic ischemic retinal disease." (PMID 36439692, 2022). "Considering all of this evidence, it seems that NO participates in the occurrence and development of myopia through S-nitrosytation modification, and ENO1 regulates this process as a target protein of S-nitrosytation modification." (PMID 36439692, 2022). "We speculate that ENO1 may mediate the occurrence and development of myopia through the dynamic regulation of S-nitrosytation modification and denitrification modification in the hypoxia signal pathway." (PMID 36439692, 2022). "ENO1 may be a key factor in the regulation of S-nitrosylation modification of myopia." (PMID 36439692, 2022). "In order to explore whether ENO1 participates in the regulation of myopia by S-nitrosytation, the expression levels of SNO-ENO1 in the retina of groups I, II, and III were further detected, and the expression level of ENO1 in the same sample was used as a reference." (PMID 36439692, 2022).
nevus (1 paper, 2022). Nevus (or naevus, plural nevi or naevi, from nævus, Latin for "birthmark") is the medical term for sharply circumscribed[1] and chronic lesions of the skin or mucosa. "The results showed that compared with that in normal benign nevus tissue samples, the levels of ENO1 and PGAM1 in SKCM tissue samples were significantly higher." (PMID 35925486, 2022). "The levels of ENO1 and PGAM1 in 12 tumor samples and nevus tissues were determined using Western blotting." (PMID 35925486, 2022).
oral epithelial dysplasia (1 paper, 2022). "Notably, the staining intensity of ENO1 in OSCC was discovered to be rather stronger than that in NOM (p < 0.001) and oral epithelial dysplasia (OED) (p < 0.05)." (PMID 36361568, 2022).
parasite (1 paper, 2024). "Meanwhile, by using protein mutation and parasite infection rate analysis, it was demonstrated that ENO1 was required for endogenous development of C. parvum." (PMID 38504274, 2024). "Expression profiles revealed significant downregulation of mRNA for proteins ENO1, ACTG1, TUBB, and TUBA3D at 3, 6, and 12 h post parasite infection, respectively." (PMID 38504274, 2024).
parasite infection (1 paper, 2024). "Conversely, the increased expression of ENO1 protein promoted the parasite infection." (PMID 38504274, 2024). "In addition, the related pathways involved in ENO1 will be required to fully understand the specific role and function mechanism of ENO1 in the parasite infection of host cells." (PMID 38504274, 2024).
prostate (1 paper, 2022). "Elevated levels of RBP4 and cadherin-2 signal early stages of prostate carcinogenesis, while ENO1, T-kininogen 2 and IDH2 represent more advanced stages." (PMID 35886909, 2022).
retinal detachment (1 paper, 2017). An eye emergency condition which may lead to blindness if left untreated. "The amount of the Eno1, vimentin, albumin and prohibitin was increased, while the amount of tubulin β‐2C, fructose‐bisphosphate aldolase A and other proteins was reduced in the retina of animals after retinal detachment." (PMID 28781956, 2017).
testicular germ cell tumor (1 paper, 2023). A germ cell tumor arising from the testis. "In addition, patients with higher ENO1 expression level had poor relapse-free survival (RFS) in BRCA, LIHC, PAAD, SARC, and TGCT (testicular germ cell tumors)." (PMID 36845730, 2023).
thyroid autoimmunity (1 paper, 2022). "The aim of the research is to study the association between the serum levels of autoantibodies against one important epitope (168FMILPVGAANFREAMR183, designated as P6) of α-enolase (ENO1-P6Abs) and miscarriage among euthyroid females with thyroid autoimmunity (TAI)." (PMID 35707546, 2022).
tubular carcinomas (1 paper, 2024). "By contrast, ENO1 is a good prognostic marker in Stage 1 disease and clusters in the context of underexpression with a wide range of the pathways in histological subtypes of BC known to be associated with a good prognosis, such as mucinous and tubular carcinomas." (PMID 39483155, 2024).
type 2 diabetes (1 paper, 2019). "Furthermore, ENO-1 inhibition turned out to be also beneficial in type 2 diabetes." (PMID 31106201, 2019).
urothelial carcinoma (1 paper, 2023). A malignant neoplasm derived from the transitional epithelium of the urinary tract (urinary bladder, ureter, urethra, or renal pelvis). "Recently, Dr. Xue-ru Wu and his associates have demonstrated that increased glycolysis by enolase-1 or pyruvate kinase 2 (PKM2) can promote tumorigenesis in mutant Ha-ras-driven urothelial carcinoma." (PMID 36838656, 2023).
varicocele (1 paper, 2020). A condition characterized by the dilated tortuous veins of the spermatic cord with a marked left-sided predominance. "The underexpressed proteins in the bilateral varicocele group compared to overexpressed proteins in unilateral varicocele were either low or very low and moderately abundant except for ENO1 and MDH2, which were highly abundant." (PMID 32365753, 2020).
viral infections (1 paper, 2022). "There are several reports which showed that ENO1 may play influential roles during viral infection by protein interactome analysis in EV-A71 infection." (PMID 35130884, 2022). "Interestingly, autophagy may bridge the mechanisms between host ENO1 and viral replication since there are some studies showed that viral infection promotes autophagy, which enhances viral replication." (PMID 35130884, 2022).